MUC1 (mucin 1, cell surface associated)
Diseases named in the same sentence as MUC1 in open-access papers (continued):
Sharing a sentence is not in itself a finding about the gene and the disease.
non-small cell lung carcinoma (57 papers, 2005 to 2026). A group of at least three distinct histological types of lung cancer, including non-small cell squamous cell carcinoma, adenocarcinoma, and large cell carcinoma. "Elevated levels of MUC1 are associated with poor prognosis for breast, prostate, ovarian, gastric, bile duct, colon, and non-small cell lung cancers." (PMID 37869082, 2023). "In line with this, MUC1 suppression has been associated with the downregulation of PD-L1 on non-small-cell-lung cancer and has augmented the anti-tumoral immune response." (PMID 33692796, 2021). "Mucin 1 (MUC1) is a cell membrane glycoprotein overexpressed in non-small cell lung cancer (NSCLC) and has been implicated in carcinogenesis of premalignant lung lesions." (PMID 30479696, 2018). "Moreover, a direct association between CA IX and MUC1 protein expression was noted in non-small cell lung cancer." (PMID 24101905, 2013). "Co-administration of PSCA and MUC1 targeted CAR T cells showed a tumor-killing effect in an in vivo mice model implanted with non-small cell lung cancer (NSCLC) cells." (PMID 39835140, 2024). "One promising endeavor is Tecemotide, focusing on MUC1 in Phase III clinical trials for stage IIIA/IIIB NSCLC (Non-small cell Lung Cancer)." (PMID 39917652, 2024). "Differential regulation of MUC1 and MUC12 in the lung has also been associated with non-small-cell lung cancer." (PMID 38245732, 2024). "Several clinical trials of MUC1 vaccines in non-small cell lung cancer (NSCLC) have also been reported." (PMID 36367122, 2023). "WWP1 interacts with the PY motif of the oncogene MUC1 to promote its ubiquitin-mediated lysosomal degradation, thus inhibiting cell proliferation and colony formation in breast cancer, liver cancer, and non-small cell lung cancer (NSCLC)." (PMID 38129384, 2023). "In patients with non-small cell lung cancer, MUC1 mRNA vaccines have been well-tolerable and induced specific-immune responses in 84% of affected patients." (PMID 33692796, 2021). "In non-small cell lung cancer patients resistant to standard anticancer therapies, a DC-based vaccine for MUC1 has improved the patients' survival." (PMID 33692796, 2021). "The glycoprotein MUC1 was evidenced to be overexpressed and aberrantly glycosylated in the patients of non-small cell lung cancer." (PMID 34138386, 2021). "Mucin 1 (MUC1) is a cell membrane glycoprotein highly expressed in many cancers including non-small cell lung cancer (NSCLC), breast, colorectal, prostate, pancreatic, ovarian, and multiple myeloma." (PMID 29385680, 2018). "Further evidence of activity in conjunction with chemotherapy was seen in another advanced non-small cell lung cancer trial utilizing the TG4010 vaccine, a recombinant virus Vaccinia Ankara encoding both MUC1 and IL-2." (PMID 26788922, 2016). "This is further supported by a similar study of non-small cell lung cancer where suppression or inhibition of MUC1 reduced EGFR signaling." (PMID 27092881, 2016). "A recombinant virus Vaccinia Ankara encoding both MUC1 and IL-2, the TG4010 vaccine, together with chemotherapy in non-small cell lung cancer showed activity." (PMID 27367740, 2016). "Currently there are promising MUC1 directed therapies being investigated in breast, ovarian and non small cell lung cancer." (PMID 18454162, 2008). "Therefore, we have found a potential immunotherapeutic strategy, which was the combination therapy with EpCAM/CD3 BsAb and MUC-1/CD3 BsAb for the treatment of non-small cell lung cancer." (PMID 34522164, 2021). "Subsequent analysis of plasma exosomes from non-small cell lung cancer (NSCLC) patients by a commercial electrochemiluminescence immunoassay showed that exosomal MUC1 level is 1.5-fold higher than healthy individuals (mean value 1.55 ± 0.16 versus mean value 1.05 ± 0.06, p = 0.0213)." (PMID 30646616, 2019).
non-small cell lung carcinoma (continued). "The vaccine TG4010, an MVA vector expressing MUC1 and IL-2, has been evaluated in 2 randomized clinical trials in combination with first-line chemotherapy for treatment of patients with advanced-stage non-small-cell lung cancer." (PMID 30626434, 2019). "MUC1 was also found to be up-regulated in non-small-cell lung cancer." (PMID 16117833, 2005). "In addition, research has shown that the co-application of prostate stem cell antigen (PSCA)-targeted and mucin 1 (MUC1)-targeted CAR-T cells effectively eradicated cancer cells in individuals diagnosed with PSCA + and MUC1 + non-small cell lung cancer (NSCLC)." (PMID 38622705, 2024). "For example, a lipid-encapsulated 25 amino acid non-glycosylated peptide (BLP25, Tecemotide) derived from the MUC1 TR demonstrated a convincing 10-month survival advantage within an 806 patient subset who received concurrent chemoradiotherapy for regionally advanced non-small cell lung cancer." (PMID 26788922, 2016). "The co-application of prostate stem cell antigen (PSCA)-targeted and mucin 1 (MUC1)-targeted CAR-T cells effectively eradicated cancer cells in individuals diagnosed with PSCA and MUC1 positive non-small cell lung cancer." (PMID 39995659, 2025). "For example, the combination of platinum-based chemotherapy and TG4010, a modified Ankara virus vaccine that expresses MUC-1 and IL-2, was investigated in a phase IIb/III trial involving patients with advanced non-small cell lung cancer." (PMID 40625850, 2025). "Mucin 1 (MUC1) and prostate stem cell antigen (PSCA) are overexpressed in non-small cell lung cancer (NSCLC)." (PMID 40092990, 2025). "In a phase 2b/3 trial for advanced non-small-cell lung cancer, TG4010 (a modified vaccinia Ankara expressing MUC1) plus chemotherapy showed a significant improvement in progression-free survival compared to a placebo plus chemotherapy." (PMID 36499455, 2022). "Our results showed that among all non-small cell lung cancer (NSCLC) patients, when the data from anti-PD-1/PD-L1, anti-CTLA-4, and anti-MUC1 drugs are combined, the mean hazard ratios (HR) of smokers and non-smokers were 0.751 and 1.016, respectively." (PMID 34575691, 2021). "In non-small cell lung cancer (NSCLC), Stimuvax is an investigational cancer vaccine that stimulates the immune response to target Mucin 1 (MUC1)." (PMID 32664247, 2020). "In a non-small cell lung cancer model, the combination of PSCA- and MUC1-targeting CAR-T cells synergistically eliminated PSCA and MUC1 positive tumor cells." (PMID 31754328, 2019). "In non-small cell lung cancer, VEGF expression and MUC1 expression were independent prognostic variables." (PMID 20492722, 2010). "The MUC1 tandem repeat non-glycosylated, lipid-encapsulated peptide (BLP25, Tecemotide) administered with chemotherapy to regionally advanced non-small cell lung cancer patients elicited a 10-month survival advantage in an 806 patient subset." (PMID 27367740, 2016).
breast tumors (45 papers, 2006 to 2025). "MUC1 is amplified in human breast tumor tissues and its overexpression was associated with worse prognosis." (PMID 35970845, 2022). "Breast tumours also display elevated and aberrant mucin-1 (muc-1) on the cell surface and are associated with poor prognosis." (PMID 36891249, 2022). "MUC1 is a transmembrane mucin, which is aberrantly overexpressed in over 90% of breast tumours and is well studied as a diagnostic marker for metastatic progression." (PMID 30361548, 2018). "The overexpression of MUC1 in transgenic mouse models is also associated with the induction of breast tumors." (PMID 22792175, 2012). "MUC1 is commonly overexpressed but under-glycosylated in primary breast tumours, and the expression of under-glycosylated MUC1 is associated with high tumour grade, metastatic potential and invasiveness of breast tumours." (PMID 26052355, 2015). "A vaccine targeting MUC1 can stimulate a tumor-specific immune response, but this effect is often suppressed within the breast tumor microenvironment." (PMID 40333213, 2025). "The high difference in DEPDC1, NUSAP1, FOXM1 and MUC1 gene expression observed between metastatic tissues and primary breast tumours can be considered as a prognostic marker for the development of metastases." (PMID 37958607, 2023). "The MUC1-conjugated aptamer interacted with the glycoprotein (MUC1) to target breast tumor cells using the self-centered aptamer attached gold nanocarrier graphene oxide nanoparticulate system." (PMID 36866455, 2023). "MUC1, an antiadhesive molecule, is overexpressed on the cell surface by breast tumor cells; thus, it inhibits cell adhesion and increases the tumor cells’ metastatic and invasive ability." (PMID 37529165, 2023). "This study also revealed that MMP1, VCAM1, FZD3, VEGFC, FOXM1 and MUC1 genes can be considered as markers of breast cancer occurrence because these genes show significant differential expression in breast neoplasms compared to normal tissue." (PMID 37958607, 2023). "Immunohistochemical staining of spontaneously developed mouse breast tumors prior to in vivo studies confirmed cross‐reactivity of nanobody with mouse MUC1 despite large structural dissimilarities between mouse and human MUC1 tandem repeats." (PMID 34694686, 2022). "APC (adenomatous polyposis coli), initially described as a tumor suppressor gene, has been shown to co-immunoprecipitate with MUC1 in human breast tumors and metastasis." (PMID 35625825, 2022). "In the presence of breast tumors, the aptamer attaches to MUC1 on the cell surface and the stimulation of Tb3+ induced fluorescence dictates the positive signal." (PMID 36430951, 2022). "Once breast tumors had developed in these mice, we treated them with the MUC1 vaccine in combination with a COX-1 and COX-2 inhibitor (indomethacin), a specific COX-2 inhibitor (celecoxib), an IDO inhibitor (1-MT) and a PGE2 receptor antagonist (AH6809)." (PMID 31693710, 2019). "In the vast majority (>90%) of adenocarcinomas, including most breast tumors, MUC1 is overexpressed and is distributed throughout the tumor mass and on the surface of tumor cells." (PMID 31693710, 2019). "These treatment regimens were explored for the treatment of orthotopic MUC1-expressing breast tumors in mice transgenic for human MUC1." (PMID 31693710, 2019). "Using these Mtag.MUC1 cells, MUC1-expressing breast tumors were generated in the immune competent MUC1.Tg mice, which carry the human MUC1 transgene driven by its own promoter." (PMID 31693710, 2019). "To this end, we developed a syngeneic murine breast tumor cell line that expresses the human form of MUC1." (PMID 31693710, 2019). "High-titre circulating anti-Mucin1 (MUC1) antibodies have been reported in human breast tumor patients." (PMID 30361548, 2018). "Our analyses of a series of breast tumor tissues demonstrated that approximately 40% of the MUC1-TM positive sections (totaling 96 different samples) were MUC1-ARF positive." (PMID 27768738, 2016).
breast tumors (continued). "Patient-derived breast tumor cells expressed high levels of the tumor antigens MUC1 and HER2/neu and HLA-A*0201+ or HLA-A*0211+." (PMID 25961716, 2015). "Transfection of C1GalT1 shRNA into MDA-MB-231 MUC1+ breast tumor cells decreased C1GalT1 protein level by 90% compared with untransfected cells." (PMID 24072600, 2013). "Analysis of the GSE5460 dataset of 76 ER+ and 53 ER− breast tumors further demonstrated that MUC1 expression is significantly higher in ER+ as compared to ER- cancers (left)." (PMID 22792175, 2012). "By this method, viral replication, and consequently extended NIS expression, will target a wide spectrum of MUC-1-positive breast tumors." (PMID 19635153, 2009). "Antibodies targeting MUC1 epitopes studied in human breast tumor biopsies bind to at least 90% of invasive breast neoplasms." (PMID 19811637, 2009). "The rationale and utility for use of this promoter is that more than 90% of breast tumors overexpress the MUC-1 gene." (PMID 19635153, 2009). "It has previously been reported that loading murine bone marrow-derived DCs with a MUC1 peptide and injecting them into mice protects the animals from subsequent challenge with MUC1-expressing breast tumours." (PMID 18253127, 2008). "Among the tumor specific CTLs, we found that CTLs specific for HLA-A2 restricted peptides derived from three well known shared breast tumor antigens, namely cyclin B1, MUC-1 and survivin." (PMID 17129372, 2006). "Among the primed CTLs, we demonstrate at least three specificities against the known shared breast tumor antigens cyclin B1, MUC-1, and survivin." (PMID 17129372, 2006). "Indeed, hyper-sialylated MUC1 on breast tumor cells drove myeloid cells towards immunosuppressive TAMs through engagement of SIGLEC9, leading to tolerance." (PMID 36891308, 2023). "This antibody targets exclusively tumor-associated MUC1 in the absence of any binding to MUC1 on healthy epithelial cells thus enabling the generation of breast tumor-specific radiolabeled immune therapeutic tools." (PMID 31588183, 2019). "However, we developed a MUC1-C specific monoclonal antibody (anti-hMUC1 monoclonal antibody) that decreases proliferation of breast cancer cells in vitro and efficiently targets MUC1 in breast tumor in a xenograft mouse model." (PMID 29987260, 2018). "In addition to recovering phages from the engraft breast tumour in round three, phages were also recovered from liver and lung tissue and used separately in biopanning against MUC1 peptides in the fourth round." (PMID 23166757, 2012). "Furthermore, MUC1, a long known cell surface marker overexpressed in a sizeable fraction of breast tumors, and KIF14, a recently proposed candidate at 1q31, presented Discriminating Scores below the threshold and were excluded from our selection." (PMID 17060936, 2006). "The results show that MUC1 and ITGB1 tended to have higher expression levels in brain metastases compared with primary breast tumors." (PMID 37108248, 2023). "One of the hypomethylated genes, MUC1 (∆Z = 1.4, FDR = 1.6E-17) is reported to be aberrantly overexpressed in over 90% of breast tumors." (PMID 35139887, 2022). "Especially, recent studies have shown that (TA)MUC1 due to its strong expression in HR-positive 35,36, HER2/neu-positive breast tumors 14 and in TNBCs 11, is crucially involved in the development of resistance to the clinically used adjuvant therapies (tamoxifen, trastuzumab, systemic chemotherapy)." (PMID 31588183, 2019). "Of note, recent studies demonstrated that macrophages isolated from human breast tumors could release epithelial growth factor (EGF), while MUC1 has been reported to enhance EGFR expression and involving in neoplasia and cell adhesion." (PMID 29423058, 2018). "To understand the in vivo role of MUC1-CD in breast development, we generated a MUC1-CD transgenic mouse model under the control of the MMTV promoter in a C57BL/6J background, which is more resistant to breast tumor." (PMID 21533058, 2011).
breast tumors (continued). "In contrast to the antibodies raised against Theratope, the antibodies cross-reacted with MUC1-Tn and stained primary breast tumours expressing STn and Tn (data not shown)." (PMID 19436292, 2009). "A dose-dependent (>15 %) binding to murine PyMTxhuMUC1 breast tumor cells which express hu(TA)MUC1 could be observed, while [89Zr]Zr-Df'-GGSK-1/30 did not bind to the murine PyMT breast tumor cells." (PMID 31588183, 2019). "The MUC1 membrane mucin expressed by luminal epithelial cells and by the bulk population of most breast tumours was also not expressed in mammospheres, but expression was induced after transferring the disrupted mammospheres to adherent plates in the presence of serum." (PMID 18541018, 2008). "The complex of aptamer–Td can adoptively attach and present doxorubicin (Dox) to MUC1 positive breast tumors, resulting in increased cytotoxicity towards MUC1-positive MCF-7 breast tumors versus normal cells, which are negative for the MUC1 marker in vitro (p < 0.01)." (PMID 36430951, 2022). "Furthermore, there are 7 literature support of genes MUC1 and HNF3-alpha related to breast neoplasm compared to 6 (MUC1) for EGFR and none for IKBKB." (PMID 18254968, 2008).
lung diseases (44 papers, 2005 to 2026). "The signal at 1q22 suggestively implicated MUC1 which encodes a cell surface glycoprotein well known to be important in several lung diseases and infections." (PMID 39974050, 2025). "A consistent fraction of these mucins is associated with diseased states, i.e., colon adenocarcinoma (MUC1, MUC2, MUC4, MUC5A/B/C), breast and uterine cancers (MUC1), and lung diseases, which may cause bronchiectasis (MUC)." (PMID 27406561, 2016). "For MUC1 and MUC5AC alleles, which had bimodal distributions, we tested “short” (S) versus “long” (L) alleles for association with CF lung disease severity." (PMID 21998660, 2011). "Several studies have shown that MUC1 acts as an anti-inflammatory molecule in several airway infections and mediates the expression of anti-inflammatory genes in lung diseases such as chronic rhinosinusitis, chronic obstructive pulmonary disease, and severe asthma." (PMID 41295249, 2025). "These were MUC1, MUC2, MUC5AC and MUC7 whose encoded proteins are of recognized importance in normal airway defense, and/or prior studies that indicate they play a role in diseases of the lung, and other inflammatory or malignant disease." (PMID 21998660, 2011). "Analysis of SNP data from candidate gene studies of MUC1, MUC2, and MUC5AC showed that none of the genotyped SNPs were highly associated with lung disease severity." (PMID 21998660, 2011).